AKT1 (AKT serine/threonine kinase 1)
Diseases named in the same sentence as AKT1 in open-access papers (continued):
Sharing a sentence is not in itself a finding about the gene and the disease.
gastric cancer (continued). "Further integrated bioinformatics and meta-analysis of multi-omics data and clinical evidence points to interconnected inflammatory and immune dysfunction centered around AKT1, IL-6, and TNF as key mechanisms linking obesity to elevated gastric cancer risk." (PMID 37954072, 2023). "In endometrial cancer, ovarian clear cell carcinoma, colon cancer, and gastric cancer, loss of ARID1A expression stimulates Akt1 phosphorylation." (PMID 36910637, 2023). "circNRIP1, a widely studied mammalian circRNA, was found to regulate the expression of AKT1/mTOR, by sponging miR-149-5p and promote gastric cancer." (PMID 36841760, 2023). "RUNX3 induces cell cycle arrest and inhibits cell proliferation of gastric cancer cells by inactivating Akt1/β-catenin/cyclin D1 signaling pathway." (PMID 38093179, 2023). "TAX significantly suppresses the proliferation and tumor formation of gastric cancer cells by inhibiting EGFR/AKT1 signaling pathway." (PMID 37567936, 2023). "At the transcriptomic level, we observed significantly increased expression of AKT1 in both the omental adipose tissue from obese patients and the tumor tissue of gastric cancer patients compared to their respective controls." (PMID 37954072, 2023). "circNRIP1, a attracted much attention circRNA, was found sponging miR-149-5p to regulate the expression of AKT1/mTOR, thereby promoting gastric cancer." (PMID 36841760, 2023). "PPI network analysis showed that the main proteins through which CKI acts on gastric cancer cells include AKT1, IL6, MAPK1, and JUN." (PMID 35590327, 2022). "Circ-NRIP1 has been shown to act as a miR-149-5p sponge, thereby suppressing autophagy through the AKT1/mTOR pathway, promoting gastric cancer (GC) cell proliferation and altered energy metabolism." (PMID 35008183, 2021). "In short, a new circular RNA circHIPK3 and its function are identified, and the regulatory pathway of circHIPK3/miR-637/AKT1 in the tumorigenesis and development of gastric cancer is discovered." (PMID 33680975, 2021). "In gastric cancer, the AKT1/NF-kB/Notch1/PTEN axis had a significant role in the development of chemoresistance." (PMID 32028262, 2020). "For instance, circNRIP1 aggravates gastric cancer progression by sponging microRNA-149-5p via the AKT1/mTOR pathway." (PMID 32831141, 2020). "Previous study indicated that miR-520a-3p diminished gastric cancer cell glycolysis and proliferation by forming feedback with AKT1/mTOR/HIF1α pathway." (PMID 33768113, 2020). "Circ_RNA circNRIP1 can sponge miRNA-149-5p to promote gastric cancer progression via regulating AKT1/mTOR signaling." (PMID 33598424, 2020). "In gastric cancer, circNRIP1 sponging microRNA-149-5p regulated the AKT1/mTOR pathway to promote progression through." (PMID 31857500, 2019). "To validate the ceRNA analysis, we made an effort to verify the specific tumour expression and prognostic role of AKT1 in gastric cancer among a large number of patients by analysing the TCGA debase." (PMID 30717751, 2019). "Of note, the higher expression of MERIT40 and poorer overall survival correlated with higher expression of Akt1 particularly in gastric cancer patients." (PMID 30065170, 2018). "The present study evaluated the effect of five selected potentially functional SNPs of AKT1 and AKT2 on risk of gastric cancer." (PMID 26818920, 2016). "In summary, the present hospital-based case-control study investigated associations between five selected potentially functional AKT1/AKT2 SNPs and gastric cancer risk." (PMID 26818920, 2016). "AKT1 knockdown in gastric cancer cells also increases the expression of Bax and reduces the expression of Bcl2, thus increasing cell death in vitro and in vivo." (PMID 26158514, 2015).
gastric cancer (continued). "AKT1 amplification is commonly observed in gastric cancer cells, and knockdown of AKT1 increases the sensitivity of gastric cancer cells to cisplatin." (PMID 26158514, 2015). "Western blotting analysis showed that GOLPH3, p-mTOR, p-Akt1, p-4EB-P1 and p-p70S6 were also expressed in the gastric cancer, carcinoma-adjacent, and paired normal gastric mucosa groups." (PMID 25286393, 2014). "The chemosensitivity of gastric carcinoma cells to cisplatin increased significantly after RNAi knockdown of Akt1 expression." (PMID 25003395, 2014). "On the other hand, amplification of Akt1 is relatively uncommon, and has been detected in only a few cases of gastric carcinoma and gliosarcoma." (PMID 24330834, 2013). "In gastric cancer, genetic mutation/amplification of PIK3CA, AKT1 and KRAS, and loss of heterozygosity of PTEN have been recognized so far." (PMID 22159814, 2012). "AKT2 mutations are much rarer than AKT1 mutations, although an AKT2 mutation has been observed before in gastric carcinoma, at a 2% frequency." (PMID 21781349, 2011). "Alternatively, amplification of AKT1 has been reported in a single case of gastric cancer, and amplification of PIK3CA associated with elevated mRNA levels has been found in 36% of gastric cancer." (PMID 15784156, 2005). "It is also reported that the growth of gastric cancer cells in mice is significantly inhibited by treatment with 25 μg/mL of taraxasterol for 16 days, and a mechanism study demonstrates that taraxasterol inhibited the growth of gastric cancer cells in mice by inhibition of EGFR/AKT1 signaling." (PMID 41374059, 2025). "Furthermore, studies have shown that circNRIP1 acts as a sponge for miR-149-5p, which leads to the activation of the AKT1/mTOR pathway, promoting the proliferation, migration, and invasion of gastric cancer cells." (PMID 40430075, 2025). "TAX prevents further progression of gastric cancer by inhibiting the EGFR/AKT1 signaling pathway." (PMID 39086391, 2024). "Furthermore, Zhang and colleagues reported that circNrip1 promoted gastric cancer progression as a microRNA-149-5p sponge through the Akt1/mTOR pathway." (PMID 35655923, 2022). "Activated AKT1 can induces the proliferation and activation of gastric cancer cells." (PMID 35672352, 2022). "The overexpression of AKT1 observed in invasive cancer cells is associated with increased expression of glucose and energy metabolism and is associated with increased glycolysis and EMT in gastric cancer cells." (PMID 33917859, 2021). "Another study confirmed that exosomal circNRIP1 could be transported between gastric cancer cells and promoted the proliferation, migration and invasion by sponging miR‐149‐5p to activate the AKT1/mTOR signalling pathway." (PMID 34672397, 2021). "A recent study confirmed that exosomal circNRIP1 could be transported between gastric cancer cells and promoted proliferation, migration and invasion by activating the AKT1/mTOR signalling pathway." (PMID 34672397, 2021). "CircNRIP1 activates AKT1/mTOR pathway by sponging miR-149-5p in gastric cancer." (PMID 31438963, 2019). "Additionally, Runx1 and Runx3 proteins have been shown to regulate the PI3K/Akt pathway in megakaryocytic leukemic and gastric cancer cell lines by directly affecting expression levels of p110 and Akt1 proteins, respectively." (PMID 24479521, 2014). "As a potential AKT1 inhibitor, adenosine may mitigate the obesity-to-gastric cancer transition." (PMID 37954072, 2023). "Moreover, circular RNA could act as a microRNA-149-5p sponge to promote gastric cancer progression via the AKT1/mTOR pathway." (PMID 35200397, 2022). "The exosomal circNRIP1 sponges miR-149-5p to promote lung metastasis in gastric cancer (GC) via the AKT1/mTOR signaling pathway in patient-derived xenograft mouse models." (PMID 36428785, 2022).
gastric cancer (continued). "Researches demonstrated that PIK3CA, PIK3CB, AKT1 and mTOR are overexpressed in GC cell lines, and mTOR pathway is active in almost 60% of gastric cancer patients." (PMID 30754640, 2019). "Through network analysis, AKT1, MAPK1, CDK2, PIK3CA, and VEGFA were found to be the key targets of HDW in the treatment of gastric cancer." (PMID 39086391, 2024). "The results showed that TS inhibited the growth of gastric cancer by down-regulating the expression of EGFR and AKT1 in cancer cells and inhibiting the EGFR/AKT1 signaling pathway." (PMID 39338278, 2024). "HZJD exerts a therapeutic effect by inhibiting AKT1 in CAG and effectively prevents the occurrence of gastric cancer." (PMID 39086391, 2024). "MTOR is a downstream molecule of AKT1, and the AKT/mTOR axis can meet the proliferation needs of gastric cancer cells via energy production activities (such as glycolysis)." (PMID 37539493, 2023). "Among these, 3 genes - AKT1, IL-6, and TNF - were shared between the obesity and gastric cancer sets." (PMID 37954072, 2023). "CircNRIP1, a circular RNA, can also be transmitted among gastric cancer cells through exosomes and regulate EMT through a circNRIP1-miR-149-5p-AKT1/mTOR axis." (PMID 34109113, 2021). "The experiments showed the overexpression of AKT1 and MTOR genes in gastric mucosa of gastric cancer patients and showed that they play vital roles in cell growth, proliferation, metabolism, angiogenesis, and survival in mediating cellular functions." (PMID 34899944, 2021). "In short, we revealed for the first time that the circHIPK3/miR-637/AKT1 regulatory pathway may be related to the tumorigenesis and growth of gastric cancer, our research results provide a potential therapeutic target for GC." (PMID 33680975, 2021). "Beclin 1 down-regulated the expression of VEGF, E-cadherin, Bcl-2, but up-regulated the expression of LC-3B, NF-κB, PI3K, Akt1/2/3 and MDR in xenograft tumor of gastric cancer cells." (PMID 33425768, 2020). "Similarly, a recent study confirmed that circNRIP1 could be transmitted by exosome connection between gastric cancer (GC) cells, and exosomal circNRIP1 sponges miR-149-5p to affect the AKT1/mTOR signaling pathway and to promote the proliferation, migration and metastasis in gastric cancer." (PMID 31277663, 2019). "Correlation between clinicopathological features and the p-AKT1, p-4E-BP1 expression in gastric cancer specimen." (PMID 25286393, 2014). "Suppression of Akt1 and PIK3R1 expression using Akt1 and PIK3R1 small hairpin RNA RNAi can inhibit gastric carcinoma cell growth in vitro and in vivo." (PMID 25003395, 2014). "Study showed that overexpression of AFP in gastric cancer patients significantly inhibited the infiltration of CD8+T cell, could promote liver metastasis by regulating the PTEN/AKT1/SOX5/CES1 signaling axis." (PMID 40900791, 2025). "The enrichment included the PI3K-Akt and IL-17 signaling pathways, and the network analysis showed that the Zhishi-Baizhu herb pair acted on seven key targets, namely, AKT1, MMP9, IL-6, CCND1, BCL2, MTOR, and MDM2 (where they played a role in treating gastric cancer)." (PMID 34899944, 2021).
gastric cancer (continued). "Bioinformatic analysis of the TCGA STAD dataset revealed that AKT3, but not AKT1 or AKT2, is upregulated in the majority of E-cadherin-deficient gastric cancers." (PMID 31540244, 2019). "To date, associations between AKT1 and AKT2 SNPs and risk of gastric cancer have not yet been clarified." (PMID 26818920, 2016). "The qRT-PCR experiments were designed to detect the expression levels of the top 5 ranking HAX1, RNF2, PIM3, TPP1 and CAV1 genes in addition to the seed proteins ABCB1, AKT1 and BCL2 in both the SGC7901 gastric cancer cell line and the Adriamycin resistant SGC7901/ADR cell line." (PMID 26039373, 2015). "In gastric cancer cells it has been shown that IGF1 is able to induce EMT through the up-regulation of ZEB2, in addition, AKT1/ERK inhibitors revert IGF1-induced EMT through up-regulation of miR-200c, suggesting the involvement of an AKT1/ERK-miR-200c-ZEB2 axis in EMT induced by IGF1 stimulation." (PMID 28880250, 2017). "We have previously shown that AKT3, but not AKT1 or AKT2, is upregulated in gastric cancers with low CDH1 expression and have identified an E-cadherin-AKT synthetic lethal relationship." (PMID 35406381, 2022).
Insulin resistance (504 papers, 2007 to 2026). Increased resistance towards insulin, that is, diminished effectiveness of insulin in reducing blood glucose levels. "Impaired AKT1 translocation to mitochondria is an intriguing paradigm underlying dysregulation of myocardial bioenergetics in the context of diabetes and insulin resistance." (PMID 37891673, 2023). "Conversely, in both rodent models of insulin deficiency (type 1 diabetes) and insulin resistance (type 2 diabetes), AKT1 translocation to mitochondria was impaired in the myocardium." (PMID 37891673, 2023). "Increased p85 and decreased p-Akt1[Ser473] are commonly associated with impaired insulin signaling, while p-Akt [Ser473] and p-eIF2α[Ser51] are also inversely related and occur with insulin resistance." (PMID 34209700, 2021). "It is evident from both human and animal research that knockdown or depletion of either Akt1 or Akt2 isoform causes glucose intolerance, insulin resistance, and diabetes-like symptoms." (PMID 34445300, 2021). "The ZnT7 null mice were susceptible to diet-induced glucose intolerance and insulin resistance and this was associated with a decrease in the expression of the insulin receptor, insulin receptor substrate 2 and Akt1." (PMID 24265765, 2013). "AKT1 rs2498786 CC genotype was a risk variant to insulin resistance and AD." (PMID 33352859, 2020). "Dysregulated AKT1 signaling contributes to neuroinflammatory processes and insulin resistance, key mechanisms linking AD and T2DM." (PMID 40823947, 2025). "In our study, AKT1 emerged as a key target of miRNAs dysregulated in both diseases, supporting its involvement in insulin resistance and neurodegeneration." (PMID 40823947, 2025). "Further, muscle‐specific overexpression of Akt1, inducing about 40% muscle growth, reduced insulin resistance." (PMID 38881251, 2024). "For instance, it has been shown that liver-specific deletion of Akt1 and Akt2 led to glucose intolerance and insulin resistance." (PMID 39325536, 2024). "Other authors suggested that ginger-derived nano particles can prevent insulin resistance in high-fat diet fed mice by increasing the expression of Foxa2 and protecting Foxa2 from AKT-1 mediated phosphorylation, ensuring inactivation of Foxa2." (PMID 38671840, 2024). "Of the three known Akt isoforms (Akt1, Akt2, and Akt3) in insulin-sensitive tissues, defects in Akt2 and Akt3 particularly impair insulin-stimulated glucose transport in insulin resistance." (PMID 39125938, 2024). "Pharmacological inhibition of AKT1 or RhoA led to improved glucose intolerance and insulin resistance." (PMID 36918564, 2023). "Most studies reporting altered insulin signaling during insulin resistance have focused on canonical insulin signaling intermediates such as AKT1,16." (PMID 36808134, 2023). "In fact, it is well known that ceramide and diacylglycerol (DAG) act as mediators of insulin resistance via the inhibition of Akt1 phosphorylation." (PMID 36829857, 2023). "It has been shown that reduced Akt1 signaling, which occurs in insulin resistance conditions, reduces mitochondrial respiration and increases in mitochondrial fission, eventually increasing oxidative stress." (PMID 37984409, 2023). "Previous studies have shown that knockdown of Akt1 or Akt 2 can result in insulin resistance and glucose intolerance." (PMID 36235831, 2022). "Among the MFS-AD targets, AKT1 occupied an important position and was also an essential part of the insulin resistance-related AD disease pathway." (PMID 36712676, 2022). "We have previously reported insulin resistance dependent decrease in serine phosphorylation of Akt1, Akt2 and Akt3 in neuronal cells.We next proceeded to test the effect of PHLPP1 silencing on Akt isoforms in neuronal insulin signaling and resistance." (PMID 36376971, 2022). "Here we show that mice with skeletal muscle-specific double knockout of Akt1/2, key downstream molecules of insulin signaling, serve as a model of premature sarcopenia with insulin resistance." (PMID 36198696, 2022).